CCND1 (cyclin D1)
Diseases named in the same sentence as CCND1 in open-access papers (continued):
Sharing a sentence is not in itself a finding about the gene and the disease.
tumor (continued). "Trop-2-triggered PKCα, tetraspanins, AKT, Jun, NF-κB, Rb, STAT1, STAT3, cyclin D1, MAPK/ERK kinases fall within main hallmarks of tumor progression, and comprise signaling networks triggered by mutated oncogenes." (PMID 37456256, 2023). "IHC staining of tumor sections revealed that the levels of ALDH1, CD44, CD133, SOX2, Notch1, EZH2 and CCND1 were downregulated in CDK5RAP2-knockdown tumors." (PMID 36774351, 2023). "Table 4also shows the concentrations of STAT3, cyclin D1, and Ki67 in the normal tissue of UTR mice and in the tumor tissue of the water-treated group of Colon26-inoculated mice." (PMID 36751299, 2023). "Further investigation demonstrated that arctiin suppresses inflammation, fibrosis, and tumor cell migration by inhibiting STAT3, TGF-β1, TLR4, NLRP3, VEGF, and cyclin D1." (PMID 37701157, 2023). "EYA1 stimulated the activity of Cyclin D1, and EYA2 inhibited the transcriptional activity of the ER-β by dephosphorylating the Y36 residue, thus promoting cancer cellular proliferation and tumor growth." (PMID 36750914, 2023). "For example, we have shown that GR can inhibit tumor cell proliferation in ER+ IDC cell lines by decreasing estrogen-mediated proliferative gene expression and G1/S cell cycle progression, including cyclin D1 (CCND1) gene expression." (PMID 37835373, 2023). "Among these genes, we identified several factors that were related to tumor progression and were found to be consistent with previously reported, for example, CAT, ATP1B1, CCND1, and CXCL12." (PMID 38020927, 2023). "Our results showing frequent loss of p16 expression in the entire tumor or focally (7/9 H3 K27M and 6/8 wt cases) have implications that should be considered more largely, as they may open the path for therapies targeting the p16 pathway (e.g., CDK4 or cyclin D1) in this population." (PMID 36900302, 2023). "Therein, PKM2 collaborates with histone H3, thereby stimulating tumor cell growth and facilitating C‐MET‐dependent synthesis of cyclin D1 and c‐Myc." (PMID 38034101, 2023). "We also detected the expression of key genes involved in Wnt/β-catenin signalling (β-catenin, lymphoid enhancer factor (LEF)-1 and cyclin D1) in SW480 cells and nude mice injected with VDR-overexpressing SW480 cells and observed tumour development." (PMID 37046222, 2023). "Cyclin D1 enhances the activity of Erα by interacting with its co-regulators, SRC1 (NCOA1) and AIB1 (NCOA3), in tumor cells." (PMID 37427143, 2023). "In PCa, the STAT protein family promotes tumor progression and mediates therapy resistance by regulating oncogene and pro-survival gene transcription (e.g., BCL2L1, MCL1, MYC, CCND1)." (PMID 35207527, 2022). "On the contrary, Kaiso has also been suggested to be a potential tumour suppressor, which repressed the transcription of MMP7, CCND1 and WNT11 genes involved in oncogenesis and metastasis." (PMID 35851744, 2022). "Edited AZIN1 is known to promote cancer cell proliferation and tumor progression through restraining antizyme-mediated degradation of oncoproteins, such as ODC and cyclin D1." (PMID 35365616, 2022). "Directly, IL-6 binds to its receptor on tumor cells and activates the STAT3 signaling pathway, which will lead to tumor progression through cyclin D1 and the proto-oncogene c-myc, an important regulator of the progression of G1 to S phase of the cell cycle." (PMID 36172343, 2022). "Tumor cells were always positive for β-catenin, CD10, CD56, cyclin-D1, progesterone receptor (PR), and vimentin by immunohistochemistry." (PMID 35204541, 2022). "The results revealed that the expression of E-cadherin was downregulated, and N-cadherin, vimentin, Cyclin D1, and pERK1/2 were upregulated in SUN5-OE tumor tissues (p < 0.05), which is consistent with in vitro results." (PMID 36358787, 2022). "Results of the present study showed that Thymax treatment significantly decreased tumor cell proliferation as indicated by marked suppression in the expression of PCNA, Ki-67, and Cyclin D1 in cancer cells." (PMID 35299600, 2022).
tumor (continued). "Paired t test analysis showed that miR-365 was significantly downregulated (paired t test, p = 0.015), and cyclin D1 was significantly upregulated (paired t test, p = 0.043) in LSCC tissues compared to that in non-tumor tissues." (PMID 35216636, 2022). "As an activator of cell cycle progression, overexpression of cyclin D1 leads to dysregulation of CDK activity, the bypass of major cell checkpoints, unlimited cell proliferation, and tumor growth." (PMID 35163589, 2022). "Previous studies demonstrated that STAT3 can directly or indirectly interact with the promoters of cyclin D1, Twist, MMP2, MMP7, MMP9, VEGF, upregulate their expression and regulate cell proliferation, tumor metastasis and angiogenesis." (PMID 36295083, 2022). "In human tumor cells, apelin induced a long-lasting activation of PI3K/Akt, upregulated β-catenin and the oncogenes c-myc and cyclin D1 and promoted proliferation, migration and glucose uptake." (PMID 36142542, 2022). "As expected, Western blot analysis of the tumor tissues showed that LLL12B suppressed the phosphorylation of STAT3 (Y705) and cyclin D1 expression." (PMID 36009550, 2022). "In line with this, the expressions of cyclin D1 and cycle-dependent kinase CDK4 were also significantly downregulated with licoricidin treatment, which promotes the exit of tumor cells from cell cycle and inhibition of cancer proliferation." (PMID 36339587, 2022). "Prior work has shown that RNA-edited AZIN1 promoted cancer cell proliferation and tumor progression through restraining antizyme-mediated degradation of oncoproteins, such as ODC and cyclin D1." (PMID 35365616, 2022). "Expression levels of ZEB1, YAP1, CCND1, and BCL2 were consistent with the database analysis and demonstrated significantly high values in tumor tissues (logFC ≥ 1.5)." (PMID 35453574, 2022). "The tested results indicated that the administration of DRB attenuated β-catenin, cyclin D1, and c-Myc expression in AOM/DSS-induced rats, which was correlated with reductions in numbers of ACFs and tumor formation in the colon." (PMID 36360101, 2022). "As such, BRAFi+MEKi therapy resistance not only reinstates tumor cell proliferation and survival, but may simultaneously dampen immune-mediated tumor control through a complex network of tumor-intrinsic transcriptional changes, that could be partly driven by an upregulation of Cyclin D1." (PMID 35444175, 2022). "Other genes, such as ETV4, ETV5, CCND1, EPHA2, and EPHA4, also play a role in activating the MAPK pathway, promoting tumor resistance to MEKi." (PMID 36437939, 2022). "The in vivo study showed that the micelles can prevent tumor progression by inhibiting the expressions of p-ERK and cyclin D1." (PMID 36304185, 2022). "Initially classified as a tumor suppressor, C53 was observed to translocate from ER to nucleus upon UFL1 depletion to inhibit cyclin D1 and cell cycle progression in glioma cells." (PMID 36743909, 2022). "The expression level of cell cycle‐related proteins, such as cyclin D1, cyclin E, Cdk2, Cdk4, Cdk6, and PCNA was also decreased in anti‐Chi3L1 antibody‐treated lung metastasis tumor tissue." (PMID 34861103, 2022). "Cyclin D1 (CCND1) was notably involved in six of the top ten pathways, indicating its complex roles in the progress of the tumor." (PMID 36438902, 2022). "Immunohistochemical staining shows that tumor cells are positive for CD10, cyclin D1 and vimentin and variably positive for WT1 and CD56." (PMID 36428715, 2022). "Most notably, we found that CCND1 and CCND2 were significantly downregulated upon PAIP1 knockdown in SMMC-7721 xenograft tumor cells, suggesting that PAIP1 promotes CCND1, CCND2, and MDM2 expression in HCC cells." (PMID 36436074, 2022). "Only one published study has proved that in the mouse xenograft model, BCL3 inhibited tumor growth via positively regulating STAT3/p-STAT3 and the downstream targets including cyclin D1." (PMID 35488886, 2022).
tumor (continued). "Given the important role of GSK-3β in cyclin D1 degradation, GSK-3β has a tumor suppressor function in HepG2215 cells." (PMID 35722140, 2022). "QKI plays a role in tumor angiogenesis via CCND1-mediated endothelial cell cycle progression by binding and stabilizing cyclin D1 mRNA; in turn, miR-200b influences cell cycle progression, angiogenesis, and metastasis by negatively regulating QKI expression." (PMID 36498861, 2022). "Among them, CCND1, GSTM1 and CYP2S1 were differentially expressed in normal tissues and tumor tissues, while the other two genes had the same expression trend as the database analysis." (PMID 36203457, 2022). "For liver tissue, relative to SKBR3 bearing tumor control, BPAF at 20 mg/kg bw/day significantly up-regulated the gene expression of four genes (MAPK3, MAPK6, EBP1, CCND1), whereas the mRNA relative levels of the other 15 genes had no a statistical difference." (PMID 36497816, 2022). "Immunohistochemical analysis of tumor tissues demonstrated that, compared to the NC group, p-STAT3, cyclin D1, and c-myc were enhanced in the Abx group but were decreased in the Abx+Stattic group." (PMID 35710492, 2022). "According to the analysis from the TCGA database, CCND1 was highly expressed, while PDCD4, as a tumor suppressor gene, was less expressed in COAD and READ than normal tissues." (PMID 36230970, 2022). "CCND1 (cyclin D1) is one of the regulators of CDK kinases by forming complexes with CDK4 or CDK6 as a subunit, whose tumor-promoting role in the development of human cancers has been intensively investigated." (PMID 35365622, 2022). "In conclusion, changes in tumor metabolism, particularly in mitochondria respiration, resulted in considerable changes in tumor characteristics through the PI3K/Akt/FoxO1/Cyclin D1 pathway." (PMID 35865479, 2022). "Spatial profiling did not further illuminate the mechanism of recurrence, since ROIs contained expression of tumor cell marker NY-ESO-1 with other oncogenic pathway markers (eg, PTEN, AKT1, and CCND1) as well as immune lineage and T-cell exhaustion markers." (PMID 35264439, 2022). "Immunohistochemically, the tumor cells showed diffuse positivity for desmin, CD56, CD57, EMA and cyclin D1." (PMID 35626339, 2022). "The decreased cyclin D1 and c‐Myc expression in NU2058‐treated cells and tumor xenografts also proved that NU2058 suppressed CRC tumor growth by inhibiting the Wnt/β‐catenin pathway." (PMID 36270974, 2022). "Some researchers have suggested that CXCR4-overexpressing cells downregulate the expression of cyclin D1 and Bcl-2 and activate other signaling pathways such as MAPK to support cell proliferation and tumor progression." (PMID 35941537, 2022). "SHP has also been shown to play a partial tumor-suppressive role, because FXR-mediated transcriptional activation of SHP inhibits the expression of cyclin D1 and C-C motif chemokine ligand 2 (CCL2), reducing the proliferation and invasion of tumor cells." (PMID 36278234, 2022). "At the same time, the apoptosis-related gene PIM1, proliferation-related gene CCND1, migration- and invasion-related gene BMPR2, and tumor immunocyte infiltration-related gene IFNAR1 also appeared in the core network." (PMID 35241097, 2022). "A recent study pointed out that overexpression of MEG3 induced G0/G1 phase arrest by downregulating cyclin D1 expression in PC3 and DU145 cells, thus inducing tumor cell apoptosis in PCa." (PMID 36544907, 2022). "Linear regression revealed that miR-675 expression was a significantly higher positive predictor than lncRNA-H19 for tumor size, pathologic grade, and AFP level; similarly, for cyclin D1 and VEGF protein expression." (PMID 36671388, 2022).
tumor (continued). "In contrast, tumour cell proliferation measured with PCNA and cyclin D1 was significantly reduced in GKO tumours compared with WT tumours in vivo." (PMID 35867177, 2022). "EGFR entering the nucleus can promote the expression of c-myc, cyclin D1, and PTGS2, and can contribute to tumor cell proliferation." (PMID 35603146, 2022). "In these cancers, the tumor suppressive role of miR-145 is achieved, at least partially, through the regulation of cell cycle-related proteins such as CDK6, CDK2, and cyclin D1, and direct targeting of oncogenes, including N-RAS and VEGF-A." (PMID 35563814, 2022). "qPCR experiments verified that the expressions of MAP7, CDK1, PPP3R1, PRKC1, CCND1 and HDAC1 genes were indeed altered in AT/RT tumor tissue." (PMID 35524230, 2022). "Western blot analysis showed that the expression of Cyclin D1 and CDK4 in tumor xenograft was inhibited by knockdown of NDUFA4." (PMID 35977935, 2022). "Immunohistochemically, tumor cells are positive for CD10, cyclin D1 and vimentin and variably positive for WT1, FOXL2, and SF1." (PMID 36428715, 2022). "Treatment with Thymax inhibited cellular proliferation by decreasing the expression of tumor markers Ki-67, PCNA, and Cyclin D1 in cancer cells and increasing the expression of p21 and p27." (PMID 35299600, 2022). "To validate changes in cell cycle and cell death pathways, we immunostained primary 4T1.13 tumours with or without knockdown of miR-21 with relevant antibodies, demonstrating that loss of miR-21 reduced markers of cell cycle progression, namely phospho-histone H3 and cyclin D1." (PMID 35821197, 2022). "In CRC, the JAK/STAT3 pathway can directly regulate tumor immune cells and upregulates the expression of oncogenic proteins, such as c-MYC, Cyclin D1, BCL2 or MCL1 to help drive tumor progression and chemoresistance." (PMID 35501324, 2022). "We also identify several segments that fall within the regulatory regions for cyclin D1, which is a known target of GATA3 in tumour cells." (PMID 35078412, 2022). "The tumor expressions of GLUT-1, Cyclin D1, TGF-α, VEGF, and EPO are specific targets of HIF-2a in chronic hypoxia when an oxidative phenotype is induced and even when tumor aggressivity and treatment resistance are high." (PMID 36294785, 2022). "As a classical tumor suppressor in multiple cancers, a recent study has revealed a certain regulatory relationship between PDCD4 and CCND1." (PMID 36230970, 2022). "Palbociclib inhibits angiogenesis and tumor progression by disrupting the miR-200b/QKI/CCND1 axis, leading to CDK 4/6-cyclin D1 complex disruption." (PMID 36498861, 2022). "STAT3 has been demonstrated to play multiple roles in cell growth, cell survival and tumour immunity through activating the transcription of various genes including c-MYC, CCND1 and Bcl-XL." (PMID 33531691, 2021). "Western blot analyses of tumor lysates confirmed the on-target activity of ATRA with decreased levels of Pin1 and its target cyclin D1." (PMID 33753863, 2021). "In breast and tumor tissues, delphinidin treatment also inhibits the expression of β-catenin, p-GSK-3β, c-Myc, cyclin-D1, and MMP-7 and upregulates miR-34a, a master regulator of tumor suppression." (PMID 33540611, 2021). "Our findings suggest that many of patients who had elevated expression of tumor‐specific signatures such as ESR1, AR, VEGF, AKT1/2/3, CCND1, CDK1, and MMP9 had significantly poorer disease‐free survivals compared with the remaining subgroups." (PMID 33275817, 2021). "Meanwhile, the expression of cell cycle-related genes such as E2F1, Cyclin D1, Cyclin B1, and CDK2 was also decreased after ITPR3 knockdown while P21, as a classical tumor suppressor gene was upregulated." (PMID 33573671, 2021).
tumor (continued). "Circ_0000677 functioned as a sponge of miR-106b and further regulated CCND1 in NSCLC cells, which promoted proliferation of tumor cells." (PMID 34519258, 2021). "In examining the dissected tumor tissues, both dipyridamole and GW4869 decreased protein contents in cyclin D1, β-catenin, YAP1, Runx2, phosphorylated Smad2/3, HMGB1, RAGE, and CD42b, except the TLR4." (PMID 33669632, 2021). "Our research found that HOXB5 inhibited the key genes CCND1 and MYC in the Wnt/β-Catenin signaling pathway, inhibited the tumor's occurrence, and inhibited the classical cancer pathway RTK pathway to inhibit cancer and improve OS." (PMID 34306077, 2021). "Actually, previous researchers have identified lncRNAs as prognostic markers of PTC, such as TTTY10, LINC00284, RBMS3-AS1, and ZFX-AS1 and five lncRNAs of PPARG, E2F1, CCND1, JUN, and EZH2 for predicting tumor recurrence in PTC." (PMID 34721037, 2021). "Let-7 miRNAs generally function as tumor suppressors to target multiple oncogenes, including RAS, HMGA2, c-Myc and CCND1." (PMID 34572067, 2021). "As compared with the control group, the levels of cyclin D1 and phosphorylation of ERK1/2 were reduced in tumor tissues of mice treated with Ag-SP-DNC." (PMID 33708128, 2021). "This was supported by the frequent (~30%) co-amplification of FGFR1 and cyclin D1/CCND1, as well as a cyclin D1 upregulation in the tumor tissues, that was examined." (PMID 34831231, 2021). "STAT3 modulates the expression of genes involved in tumor development and progression, including VEGF, c-Myc, cyclin D1 and survivin." (PMID 34360552, 2021). "In contrast, circNR3C1 is dramatically reduced in BC, and it impairs the growth of BC tumor cells by restraining miR-27a-3p to inhibit its interactions with CCND1 and thus suppress cyclin D1 expression." (PMID 34869591, 2021). "Genes of interest involved in tumor progression or uterine fibroids, from previous studies, FGFR1, CCND1, PCDH11X, VDR, NDRG2 and INPP4B, are indicated in the volcano plot." (PMID 33807176, 2021). "Some NF-κB target genes such as CCND1, BCL2L1 and GADD45B and ICAM1 which are responsible for proliferation, anti-apoptosis and adhesion were also upregulated in the tumor tissues." (PMID 33144684, 2021). "Serum reduction of U87MG 2D cultures or multi‐cellular tumour spheroids induced a quiescent like state characterized by increased DYRK1B and p27, and decreased pRb and cyclin D1." (PMID 34708541, 2021). "Our data show for the first time that increasing miR-342-5p intrinsically reduces imatinib resistance in CMLMiR-342-5p acts as a tumor suppressor in CML by suppressing the expression of BCR-ABL and CCND1." (PMID 34611140, 2021). "We examined protein expression in B, T, and PDX samples for CCND1, KI67, CD34, GPC3, YAP, and EZH2 to provide loose validation of different tumor clusters." (PMID 34497364, 2021). "The following factors were included as explanatory variables: sex, age, tumor site, tumor size, TNM stage, and CDK4/cyclin D1 expression." (PMID 34395284, 2021). "Mechanistic investigations demonstrated that the miR-197-mediated CKS1B/STAT3 axis was excavated exerting tumor progression regulated by various protooncogenes like BCL2 Apoptosis Regulator (BCL2), MYC, and Cyclin D1(CCND1)." (PMID 34925510, 2021). "The most important molecules are Cyclin-D1 and CDK2, which are essential proteins for tumor cells to enter the G1 phase to the S phase and to switch from the S phase to the G2 phase." (PMID 34319912, 2021). "One study using a single cell line, A431, showed that oestrogen receptors ERα and G‐coupled protein receptor (GPR30, or GPER1) modulated expression of tumour markers Cyclin D1 and CD55; however, ERβ downregulated both tumour markers." (PMID 35664979, 2021).